SLPI (secretory leukocyte peptidase inhibitor)
Description:
Acid-stable proteinase inhibitor with strong affinities for trypsin, chymotrypsin, elastase, and cathepsin G. Modulates the inflammatory and immune responses after bacterial infection, and after infection by the intracellular parasite L.major. Down-regulates responses to bacterial lipopolysaccharide (LPS) (By similarity). Plays a role in regulating the activation of NF-kappa-B and inflammatory responses. Has antimicrobial activity against mycobacteria, but not against salmonella. Contributes to normal resistance against infection by M.tuberculosis. Required for normal resistance to infection by L.major. Required for normal wound healing, probably by preventing tissue damage by limiting protease activity (By similarity). Together with ELANE, required for normal differentiation and proliferation of bone marrow myeloid cells.
Synonyms: ALP; MPI; WAP4; WFDC4; HUSI-I; ALK1; BLPI; HUSI; HUSI-1
Tractability: Antibody: UniProt places it where antibodies can reach, with high confidence; its Gene Ontology location is reachable by antibodies, with high confidence; UniProt predicts a signal peptide or a membrane-spanning region.
Gene: Protein-coding gene on chromosome 20 (45,252,239 to 45,254,564, reverse strand). Ensembl gene ENSG00000124107.
Subcellular location: Secreted
Subcellular location (Human Protein Atlas): Golgi apparatus; Predicted to be secreted
Pathways (Reactome):
Developmental Biology: Developmental Lineage of Mammary Gland Alveolar Cells; Developmental Lineage of Mammary Gland Luminal Epithelial Cells
Immune System: Neutrophil degranulation
Gene Ontology:
Molecular function: DNA binding; endopeptidase inhibitor activity; enzyme binding; mRNA binding; protein binding; serine-type endopeptidase inhibitor activity; peptidase inhibitor activity
Biological process: antibacterial humoral response; host-mediated perturbation of symbiont process; negative regulation of protein binding; negative regulation of viral genome replication; immune response; innate immune response; response to lipopolysaccharide
Cellular component: extracellular exosome; extracellular matrix; extracellular region; specific granule lumen
Genetic constraint (gnomAD): Loss-of-function variants: 20 observed, 15.68 expected, observed/expected ratio (o/e) 1.28, 90% interval 0.89 to 1.79. The upper end of that interval is the gene's LOEUF score, 1.79, which puts it in group 6 of 6, group 1 being the genes least tolerant of losing a copy. Missense variants: 169 observed, 167.31 expected, observed/expected ratio (o/e) 1.01, 90% interval 0.89 to 1.15. Synonymous variants: 68 observed, 58.19 expected, observed/expected ratio (o/e) 1.17, 90% interval 0.96 to 1.43.
Homologues: Orthologues: chimpanzee SLPI (99% identical), macaque SLPI (89% identical), pig SLPI (70% identical), dog SLPI (62% identical), rat Slpi-ps1 (62% identical), guinea pig SLPI (61% identical), mouse Slpi (58% identical), rat Slpi (58% identical), rat Slpi-ps2 (55% identical), rat Slpi-ps2 (53% identical), Drosophila melanogaster CG5639 (37% identical), Caenorhabditis elegans C08G9.2 (27% identical). Paralogues in human: WFDC3 (33% identical), WFDC5 (31% identical), PI3 (30% identical), WFDC12 (22% identical), WFDC13 (16% identical), WFDC9 (12% identical), WFDC10A (11% identical), WFDC11 (11% identical), WFDC10B (10% identical).
Diseases named in the same sentence as SLPI in open-access papers:
SLPI is named in the same sentence as 153 diseases in open-access papers, as found by Europe PMC text mining. Sharing a sentence is not in itself a finding about the gene and the disease. The quoted sentences say what the papers report.
ovarian carcinoma (26 papers, 2008 to 2025). A malignant neoplasm originating from the surface ovarian epithelium. "SLPI is upregulated in human ovarian cancer cells upon exposure to paclitaxel and overexpression of SLPI is associated with paclitaxel resistance via MEK/ERK-dependent pathway." (PMID 36077500, 2022). "Elevated gene expression of SLPI has been associated with cancer cell growth and metastasis in ovarian cancer." (PMID 25110884, 2014). "CAFs secrete collagen response medium protein 2 (CRMP2), secretory leukocyte protease inhibitor (SLPI), etc., which can promote the progression of ovarian cancer through specific signaling pathways." (PMID 40104498, 2025). "Modulated expression of SLPI has been reported in various human malignancies, such as gastric cancer, thyroid cancer, lung cancer, ovarian cancer, endometrial cancer, and oral cancer." (PMID 36812122, 2023). "A small number of studies have found that SLPI can be involved in the progression of ovarian cancer by regulating ERK MAPK signaling pathway 27, and it can also be involved in myocardial ischemia/reperfusion injury by regulating the p38 MAPK signaling pathway." (PMID 34975323, 2022). "SLPI promotes ovarian cancer cell growth, prevents apoptosis in vitro and exerts a pro-metastatic function via increasing MMP-9 production in vivo." (PMID 36077500, 2022). "There is a rich literature available substantiating that SLPI is overexpressed in diverse cancers, including gastric cancer, ovarian cancer, and pancreatic cancer." (PMID 36588538, 2022). "In some high-risk, aggressive or metastatic tumors, such as the pancreatic, uterine cervix, papillary thyroid, and ovarian cancers, SLPI was often found to be highly expressed." (PMID 33381555, 2020). "SLPI was increased in ovarian cancer and enhances the invasiveness of ovarian cancer cells via modulating MMP-9 release." (PMID 32742768, 2020). "For example, SLPI promoted proliferation and survival of ovarian cancer cells through partnering with prgn." (PMID 31462893, 2019). "Recent reports revealed that SLPI is also overexpressed in gastric, lung and ovarian cancers, which accelerates the metastasis of cancer cells." (PMID 25954138, 2015). "High levels of serum SLPI were significantly elevated in ovarian cancer patients compared with benign control." (PMID 21179408, 2010). "SLPI has already been described for its cancer-promoting ability, and its increased expression has been found in several tumours, including lung, pancreatic, gastric, breast and ovarian cancer, related to tumour progression." (PMID 38969699, 2024). "Previously, an inhibitory role of PI3 in cisplatin-induced apoptosis has been reported in ovarian cancer cells, whereas SLPI inhibited TNFα-induced apoptosis in lymphoma-derived U937 cells; however, a role for apoptosis regulation in brain tumors has not been addressed before." (PMID 37158962, 2023). "In ovarian cancer, secretory leukocyte protease inhibitor (SLPI) protein derived from FAPhigh α-SMAlow CAFs can be encapsulated in extracellular vesicles (EVs) and delivered to cancer cells, promoting cell proliferation, adhesion, invasion, and migration via the PI3K/AKT signaling pathway." (PMID 37143134, 2023). "It has been reported that the expression of SLPI is up-regulated in some types of tumors such as non-small cell lung cancer, prostate cancer, inflammatory breast cancer and ovarian cancer, which could play a promoting role in tumor progression 19-21." (PMID 34975323, 2022). "In addition, SLPI was shown to stimulate ovarian cancer invasion and this function was partly mediated by its serine protease inhibitory activity attenuating MMP-9 release." (PMID 31462893, 2019). "SLPI was found to be highly expressed in ovarian cancer cells and its expression may promote cancer progression." (PMID 31404090, 2019).
ovarian carcinoma (continued). "The study comprehensively investigates the roles of SPP1, SLPI, and CD9 in ovarian cancer, providing insights into their functions in skeletal development, immune regulation, and tumor progression." (PMID 40196737, 2025). "The link between SLPI and MMP-9 was reported in the context of cancer cell lines where it has been shown that SLPI can either limit MMP-9 secretion in ovarian cancer or promote MMP-9 in gastric cancer." (PMID 40496854, 2025). "In this study, nanobodies targeting human HE4, SLPI, and PGRN ovarian cancer antigens were explored with respect to their bacterial expression yield, antigen-binding affinity, and antigen competition." (PMID 36430166, 2022). "For ovarian cancer, the tags CAACTAATTC and TGTGGGAAAT belong to the clusterin (CLU) and secretory leukocyte peptidase inhibitor (SLPI) genes, respectively." (PMID 21179408, 2010). "This study investigated three key genes in ovarian cancer (OV), namely, SPP1, SLPI, and CD9." (PMID 40196737, 2025). "SPP1, SLPI, and CD9 and their mechanisms of action may be potential targets for the treatment of ovarian cancer with succinic acid." (PMID 40196737, 2025).
breast carcinoma (21 papers, 2012 to 2025). "Overexpression of SLPI has been associated with the metastasis of breast cancer, gastric cancer, and malignant glioma, wherein it degrades the basement membrane and promotes the aggressiveness of these tumor types." (PMID 33511023, 2021). "This analysis showed that higher SLPI expression (mRNA level) in tumor samples is associated with shorter overall survival of patients with breast cancer in general, as well as in the subset with basal/TNBC." (PMID 29312532, 2017). "In breast cancer, overexpression of SLPI is usually associated with more aggressive, metastatic disease." (PMID 29312532, 2017). "Like SLPI, progranulin has been associated with aggressive tumorigenesis by promoting invasiveness of breast cancer cells." (PMID 25110884, 2014). "SLPI has been demonstrated to be down-regulated in nasopharyngeal carcinoma, bladder cancer, prostate cancer and breast cancer 12-14." (PMID 34975323, 2022). "A recent study has identified SLPI as a new target for anti-metastatic therapies due to its pro-metastatic part of secretome for breast cancer, chiefly for TNCs." (PMID 33593445, 2021). "Both distant metastasis-free survival and overall survival were found to be significantly worse in the Basal/TNBC subtype of breast cancer patients with higher SLPI expression in tumor samples." (PMID 29312532, 2017). "First, we found overexpression of SLPI facilitated breast cancer cell invasion of an endothelial monolayer." (PMID 29312532, 2017). "In animal studies, overexpression of SLPI in implanted breast cancer cells typically lead to enhanced local growth and increased metastasis, but the opposite effect at the primary site has also been reported." (PMID 29312532, 2017). "In this study, we identify SLPI as an important pro-metastatic component of the secretome for breast cancers, primarily for TNBCs." (PMID 29312532, 2017). "In cancer, there is a body of literature showing increased SLPI expression not only in breast cancer, but also in lung, gastric and colorectal carcinomas." (PMID 29312532, 2017). "Our results on breast cancer cells are in line with that observations and directly link SLPI expression to regulation of FoxM1 function." (PMID 29312532, 2017). "Connective tissue growth factor (CTGF) has been suggested as a tumor suppressor in human breast cancer and the secretory leukocyte protease inhibitor (SLPI) that enhances tumor aggressiveness through vascular mimicry." (PMID 27179633, 2016). "Our results demonstrate that secretion of SLPI is drastically increased in highly metastatic cells, suggesting a possible role for SLPI in enhancing the metastatic behavior of breast cancer cell line 4T1." (PMID 25110884, 2014). "This increased SLPI level was not only observed in cells grown in tissue culture media, but also in breast carcinomas generated from these cells in vivo." (PMID 25110884, 2014). "Further work is necessary to determine the biological role of SLPI in breast cancer progression to metastasis." (PMID 25110884, 2014). "However, in bladder tumors, nasopharyngeal carcinoma, and some breast cancers, SLPI has a low expression." (PMID 33381555, 2020). "In breast cancer cells, SLPI exerted pro-apoptotic and cell cycle-arrest effects." (PMID 31462893, 2019). "To determine whether SLPI expression levels correlate with clinical outcome in breast cancer patients, we used the Kaplan-Meier Plotter, a freely available online tool, for survival analysis of data collected in its database." (PMID 29312532, 2017). "To determine whether SLPI interacts with Rb, we used protein extracts from two different breast cancer cell lines." (PMID 29312532, 2017). "To confirm that SLPI could also be detected in the nucleus of cancer cells, we immunostained breast cancer cells with anti-SLPI antibody." (PMID 29312532, 2017).
breast carcinoma (continued). "Here, we show that highly metastatic murine 4T1 TNBC breast cancer cells produce higher levels of SLPI compared to their non-metastatic 67NR counterparts and that SLPI level is associated with increased lung metastasis from orthotopically implanted 4T1 tumors." (PMID 29312532, 2017). "Additionally, SLPI emerged as the most significantly gene in human breast cancer patients that had lung-metastatic relapses." (PMID 27179633, 2016). "SLPI is upregulated in a highly metastatic breast cancer cell line." (PMID 23502467, 2013). "Moreover, stable transfection experiments demonstrated that overexpression of either mouse or human SLPI led to increased tumorigenicity and lung-colonization potential of a low grade breast cancer cell line." (PMID 23502467, 2013). "From the downregulated genes of the EMT-core gene list, low FXYD3 expression showed a trend to poor overall survival of SCC patients (p = 0.17) and low expression of LAD1 (p = 0.00074), SLC7A5 (p = 0.0093) and SLPI (p = 0.043) significantly correlated with worse pCR of breast cancer patients." (PMID 23251436, 2012). "We also discovered that SLPI physically interacts with the retinoblastoma tumor suppressor protein (Rb) and releases FoxM1 from the Rb-FoxM1 complex, which may activate FoxM1 target genes involved in breast cancer metastasis." (PMID 29312532, 2017). "Altered expressions of SLPI and elafin have been identified in several carcinomas, and it appears that these aberrations may play a role in tumor formation, stimulation of metastatic potential, and development of malignant behavior in cancer cells, including breast cancer (BC)." (PMID 34306124, 2021). "To test the feasibility of our results in CD24+ human breast cancer cells, we downregulated IGF1R in the MCF7 cells and identified a marked reduction in SLPI levels." (PMID 27179633, 2016). "Comparison of the secreted proteins from the mouse breast cancer cell line 4T1 and its highly metastatic 4T1.2 clone revealed a prominent differentially secreted protein which was identified as SLPI (secretory leukocyte protease inhibitor)." (PMID 25110884, 2014). "We were able to show that FXYD3 and PTX3 expression is associated with poor overall patient survival in SCC patients and LAD1, SLC7A5, SLPI, NID2, SPOCK1 and SULF1 correlated significantly with impaired pCR in breast cancer patients." (PMID 23251436, 2012). "To investigate which, if any, of the three proteins secreted by the metastatic breast cancer cells (SLPI, TSLP, and G-CSF) have a functional role in tumor growth and metastasis, we next used lentivirally-transduced shRNA to stably inhibit translation of SLPI, TSLP, or G-CSF in 4T1 cells." (PMID 29312532, 2017).
gastric cancer (17 papers, 2011 to 2025). A primary or metastatic malignant neoplasm involving the stomach. "Upregulation of SLPI is associated with the progression of gastric cancer and development of pancreatic ductal adenocarcinoma (PDAC)." (PMID 32742768, 2020). "IL-17 upregulates the expression of SLPI and counteracts the inhibitory effect of cisplatin on gastric cancer cells." (PMID 39676857, 2024). "Transfected SLPI‐siRNA in gastric cancer cell lines resulted in significantly reduced MMP2 and MMP9 expression, as well as cell migration and invasion rates." (PMID 34580954, 2021). "SLPI has high expression in gastric cancer cells with serosa invasion, and SLPI overexpression in gastric cancer cell lines can improve the cell migration and invasion rate." (PMID 33381555, 2020). "SLPI mRNA was overexpressed in serosa invading gastric cancer cells, and the cell migration and invasion rate was significantly increased in SLPI overexpressing gastric cancer cell line." (PMID 28255192, 2017). "Earlier studies by our group have shown that SPARC, CLIC1, SLPI, CXCL1, CXCL8, and CXCR2 are highly expressed and associated with advanced stages and poor prognosis of gastric cancer." (PMID 22479608, 2012). "SLPI promoted migration, invasion and metastasis of gastric cancer cells by increasing expression of MMP-2 and MMP-9 genes, and the latter could have been targeted by transcriptional factor FoxM1." (PMID 29312532, 2017). "Moreover, a more direct link with MMP-9 was found whereby SLPI was shown to promote the metastasis of gastric cancer cells by increasing MMP-9 expression." (PMID 28561062, 2017). "Also, overexpression of the SLPI in gastric cancer cells increased the expression of FoxM1 target genes iMMP-2 and MMP-9 and promoted the migration of cancer cells by degrading collagen but FoxM1 was not examined." (PMID 29312532, 2017). "Consistent with its tumor suppressor potential, ectopic expression of latexin induced differential expression of several tumor related genes, including Maspin, WFDC1, SLPI, S100P, and PDGFRB, in gastric cancer cells." (PMID 21466706, 2011). "Using the top eight upregulated genes (SLPI, PLA2G2A, CXCL1, CCL20, REG1A, CLDN7, PI3, LGALS3) as a representative gene set for the high metabolic subcluster, we calculated the GSVA score of this gene set for each patient in the TCGA gastric cancer cohort." (PMID 38831933, 2024).